MARCHF6 (membrane associated ring-CH-type finger 6)
Description:
Endoplasmic reticulum membrane-associated E3 ubiquitin ligase that plays a critical role in mitigating endoplasmic reticulum stress, the regulation of cholesterol and lipid homeostasis, and ferroptosis. Acts as a pivotal component of both the Ac/N-degron pathway (targeting the N-terminal acetyl group of substrates) and the ER-associated protein degradation-cytosol (ERAD-C) pathway (targeting misfolded substrates). For instance, mediates the degradation of Ac/N-degron-bearing proteins such as the G protein regulator RGS2 and the lipid droplet protein PLIN2. Suppresses endoplasmic reticulum stress and ferroptosis through cytosolic POMC degradation (By similarity). Prevents ferroptosis by acting as a NADPH sensor during lipid peroxidation through its C-terminal regulatory region. Facilitates also the degradation of selected endoplasmic reticulum proteins by associating with signal peptide peptidase for the turnover of endogenous tail-anchored proteins. Promotes ubiquitination of DIO2, leading to its degradation. By ubiquitinating and thereby modulating the stability of many proteins of the cholesterol pathway including SQLE, CYP51A1, CYP11A1 and HMGCR, acts as a crucial post-translational regulator of cholesterol synthesis.
Synonyms: MARCH-VI; MARCH6; RNF176; TEB4; DOA10; FAME3; FCMTE3
Tractability: Antibody: UniProt predicts a signal peptide or a membrane-spanning region. PROTAC: UniProt records ubiquitination sites on it; ubiquitination databases record sites on it.
Gene: Protein-coding gene on chromosome 5 (10,353,695 to 10,440,388, forward strand). Ensembl gene ENSG00000145495.
Subcellular location: Endoplasmic reticulum membrane
Subcellular location (Human Protein Atlas): Endoplasmic reticulum
Pathways (Reactome):
Metabolism of proteins: ER Quality Control Compartment (ERQC)
Gene Ontology:
Molecular function: enzyme binding; protein binding; ubiquitin conjugating enzyme binding; ubiquitin protein ligase activity; ubiquitin-protein transferase activity; ubiquitin-specific protease binding; zinc ion binding
Biological process: negative regulation of cholesterol biosynthetic process; proteasomal protein catabolic process; proteasome-mediated ubiquitin-dependent protein catabolic process; protein K48-linked ubiquitination; protein ubiquitination; endoplasmic reticulum mannose trimming; ERAD pathway
Cellular component: endoplasmic reticulum; endoplasmic reticulum membrane; membrane; ER ubiquitin ligase complex; endoplasmic reticulum quality control compartment
Genetic constraint (gnomAD): Loss-of-function variants: 19 observed, 88.83 expected, observed/expected ratio (o/e) 0.21, 90% interval 0.15 to 0.31. The upper end of that interval is the gene's LOEUF score, 0.31, which puts it in group 1 of 6, group 1 being the genes least tolerant of losing a copy. Missense variants: 551 observed, 873.36 expected, observed/expected ratio (o/e) 0.63, 90% interval 0.59 to 0.68. Synonymous variants: 303 observed, 332.31 expected, observed/expected ratio (o/e) 0.91, 90% interval 0.83 to 1.
Homologues: Orthologues: macaque MARCHF6 (99% identical), chimpanzee MARCHF6 (99% identical), dog MARCHF6 (99% identical), pig MARCHF6 (98% identical), rabbit MARCHF6 (98% identical), mouse Marchf6 (98% identical), rat Marchf6 (98% identical), guinea pig MARCHF6 (96% identical), tropical clawed frog marchf6 (91% identical), zebrafish marchf6 (89% identical), Drosophila melanogaster CG1317 (52% identical), Caenorhabditis elegans marc-6 (42% identical).
Diseases named in the same sentence as MARCHF6 in open-access papers:
MARCHF6 is named in the same sentence as 29 diseases in open-access papers, as found by Europe PMC text mining. Sharing a sentence is not in itself a finding about the gene and the disease. The quoted sentences say what the papers report.
epilepsy (3 papers, 2025). A brain disorder characterized by episodes of abnormally increased neuronal discharge resulting in transient episodes of sensory or motor neurological dysfunction, or psychic dysfunction. "Familial Adult Myoclonic Epilepsy type 3 (FAME3) is a rare autosomal dominant disorder characterized by cortical tremor and epilepsy, caused by a noncoding pentanucleotide repeat expansion (TTTTA/TTTCA)n in the MARCHF6 gene." (PMID 40788430, 2025).
atherosclerosis (2 papers, 2024 to 2025). A disease characterized by the build-up of fatty material and calcium deposition in the arterial wall resulting in partial or complete occlusion of the arterial lumen. "Of them, Ctnnd2, Dap, Marchf6, Cmbl, Sdc2, Cpq, Stk3, Vps13b, Cox6c, Grhl2, Fzd6, Cthrc1, Lrp12, and Zfpm2 showed associations or had functions related to atherosclerosis or obesity." (PMID 40362477, 2025).
tumor (5 papers, 2021 to 2023). "The latest study published on Nature cell biology by Nguyen and colleagues found a new NADPH sensor, MARCHF6 an E3 ubiquitin ligase, mediates ferroptosis in tumor growth and animal development." (PMID 36266653, 2022). "For example, membrane-associated ring-CH-type finger 6 (MARCHF6), an E3 ubiquitin ligase, interacts with nicotinamide adenine dinucleotide phosphate (NADPH) to enhance its own activity while mediating the degradation of ACSL4 to inhibit ferroptosis in tumor cells." (PMID 37372148, 2023).
cancer (4 papers, 2021 to 2025). A tumor composed of atypical neoplastic, often pleomorphic cells that invade other tissues. "Understanding the intricate role of MARCHF6 and its various substrates can provide further insights into understanding the molecular basis of regulation of ferroptosis in the context of cancer cell biology and neurodegeneration." (PMID 40643475, 2025).
genetic disorders (1 paper, 2025). "We demonstrate that long-read sequencing (LRS) successfully identified a pathogenic repeat expansion in MARCHF6, confirming the diagnosis of FAME3 and highlighting the diagnostic power of LRS in complex genetic disorders." (PMID 40788430, 2025).
MARCHF6 also shares sentences with these, for which no sentence is quoted: breast carcinoma (3 papers); prostate carcinoma (3); adult familial myoclonic epilepsies (2); hepatocellular carcinoma (2); Obesity (2); renal carcinoma (2); adenoma (1); arteriopathy (1); colonic adenomas (1); Friedreich ataxia (1); Fuchs endothelial corneal dystrophy (1); heart failure (1); infarction (1); infection (1); Insulin resistance (1); liver disease (1); Myoclonus (1); papillary carcinoma (1); papillary thyroid cancers (1); Progressive myoclonic epilepsy (1); spinocerebellar ataxia type 37 (1); thyroid (1); thyroid cancer (1); viral infection (1).